CRP (C-reactive protein)
Diseases named in the same sentence as CRP in open-access papers (continued):
Sharing a sentence is not in itself a finding about the gene and the disease.
Hypoalbuminemia (continued). "Patients with KDSS have been reported to have increased incidence of gastrointestinal manifestations, hyponatremia, anemia, thrombocytopenia, hypoalbuminemia, elevated inflammatory markers (e.g., neutrophila, high CRP, ESR), IVIg resistance, CAAs (up to 65%), morbidity and mortality (up to 6.8%)." (PMID 33072669, 2020). "In contrast, mGPS is based on a combination of elevated CRP and hypoalbuminemia." (PMID 32441463, 2020). "However, patients with hypoalbuminemia were more likely to have pulmonary oedema on chest X-ray, as well as higher levels of NT-proBNP and CRP, and lower levels of haemoglobin at baseline." (PMID 31095609, 2019). "A high GPS was defined as the presence of hypoalbuminemia and an increased serum level of CRP." (PMID 30046949, 2019). "In addition, normalization of more than 25% hypozincemia, hypoalbuminemia and high CRP cases was observed." (PMID 31694220, 2019). "The inflammation-based Glasgow Prognostic Score (GPS) is a scoring system combining elevated C-reactive protein (CRP) serum levels and hypoalbuminemia, factors for inflammation and hypermetabolism, used to stratify patients into risk groups for predicting clinical outcome." (PMID 30535923, 2019). "Additionally, there were more patients with positive changes in BMI Z-score and normalization of hypoalbuminemia, hypozincemia and high CRP status in group A than B." (PMID 31694220, 2019). "In the beginning, there were three patients with hypozincemia, hypoalbuminemia and a high CRP." (PMID 31694220, 2019). "However, when inflammation is accompanied, protein production in the liver is inclined to the production of acute-phase proteins including CRP, accompanied by stress-induced hypoalbuminemia, which results in decreased production of Alb." (PMID 31038863, 2019). "The patient cohort undergoing palliative surgery had a higher proportion of males (p = 0.002), raised serum CRP measurements (p = 0.003), hypoalbuminaemia (p = 0.024), higher mGPS (p = 0.001), and a fewer patients had undergone neoadjuvant chemotherapy (p = 0.024)." (PMID 29234999, 2018). "The present patient presented with elevated CRP levels, hypoalbuminemia, and renal injury." (PMID 30419835, 2018). "Also, previous reports have demonstrated that elevation of CRP levels, hypoalbuminemia, and renal injury are candidate factors affecting the occurrence of PRES." (PMID 30419835, 2018). "Laboratory examination revealed elevated white blood cell count (WBC) at 20 × 109/L and C-reactive protein (CRP) at 224 mg/L along with increased liver function tests (Alanine aminotransferase at 84 U/L and Alkaline phosphatase at 256 U/L) and hypoalbuminemia at 19 g/L." (PMID 29329519, 2018). "Therefore, the presence of a systemic inflammatory response, as indicated by elevated CRP level and hypoalbuminemia, should be routinely evaluated prior to surgery." (PMID 29335491, 2018). "No statistical significance regarding OS could be found in the multiple Cox proportional hazards model for elevated preoperative CRP (HR 1.47; 95% CI, 0.97–2.24; p = 0.07) and preoperative hypoalbuminemia (HR 0.92; 95% CI, 0.54–1.58; p = 0.76)." (PMID 28740506, 2017). "The preoperative CNG was calculated as follows: patients with hypoalbuminemia (< 35 g/L), elevated C-reactive protein (> 10 mg/L), and elevated NLR (≥ 2) were allocated a score of 3; patients with two, one, or no abnormal values were allocated a score of 2, 1, or 0, respectively." (PMID 28358923, 2017). "Transferrin depletion also affected more patients than hypoalbuminemia or elevated CRP levels." (PMID 28866982, 2017). "Of the 22 patients with hypoalbuminemia, 21 (95.45%) had an elevated CRP concentration." (PMID 28431566, 2017). "In addition to classical predictive factors such as the cardiac biomarkers NTproBNP and troponin, inflammation markers (C-reactive protein) and hypoalbuminemia, we also took heart failure into account, which to our knowledge has not previously been done." (PMID 27415758, 2016).
Hypoalbuminemia (continued). "Consequently, careful monitoring of voriconazole concentration and side effects are required for patients with both elevated CRP level and hypoalbuminemia." (PMID 27096102, 2016). "In light of our study elevated CRP combined with hypoalbuminemia and tumour markers might be helpful for selecting patients for surgery, especially in borderline cases." (PMID 27632196, 2016). "Therefore, we propose that early measurement of voriconazole concentration before the plateau phase should lead to the avoidance of toxic voriconazole level in patients with elevated CRP level and hypoalbuminemia." (PMID 27096102, 2016). "Additionally, preoperative CRP, PCT, TLC, and hypoalbuminemia were found to be significant factors associated with SSIs emerging from univariate analysis." (PMID 27399098, 2016). "Besides CRP and hypoalbuminemia, elevation of the tumour markers CA19-9 and CEA correlated independently with worse prognosis." (PMID 27632196, 2016). "Furthermore, the suitable cut-off values should be 10 mg/L for elevated CRP level and 35 g/L for hypoalbuminemia." (PMID 26752624, 2016). "In conclusion, this large retrospective study of patients with resectable PDAC shows that elevated CRP and hypoalbuminemia, as well as the GPS based on these parameters, were independent prognostic markers, indicating that preoperative cancer-related SIR is predictive of worse survival." (PMID 27632196, 2016). "The primary endpoint of this study was to reveal whether antecedent CRP could be used to predict future hypoalbuminemia in the perioperative period of colorectal surgery." (PMID 26530188, 2015). "After adding GI symptom score or CRP into the regression analysis, neither factor attenuated the association between lower eGFR and lower albumin or hypoalbuminemia (pathway 5)." (PMID 26651991, 2015). "In the evaluation of GPS, a prognosticscore that ranks inflammatory response based on a combination of CRP and albuminresults, 7 (15%) patients were GPS 2 (hypoalbuminemia and increased CRP), 26 (54%)were GPS 1 (high PCR or hypoalbuminemia), and 15 (31%) were GPS 0 (no changes)." (PMID 26270855, 2015). "Hypoalbuminemia, upper quartile CRP, and detectable LPS improved TB risk discrimination the most, albeit minimally, among all biomarkers when added to this model (AUC with hypoalbuminemia 0.84, 95% CI: 0.79–0.89; AUC with CRP 0.85, 95%: CI 0.79–0.90, AUC with detectable LPS 0.84, 95% CI: 0.79–0.89)." (PMID 25719208, 2015). "Therefore, the results of the present study are important, indicating significant association not only between RDW and CRP but also between RDW and hypoalbuminemia, which is indicative of malnutrition and mortality." (PMID 26321026, 2015). "The primary endpoint of this study was to reveal that antecedent CRP could be utilized to predict future hypoalbuminemia in the perioperative period of colorectal surgery." (PMID 26530188, 2015). "Roxburgh and McMillan showed that, in primary operable cancer, preoperative estimation of the systemic inflammatory response such as elevated CRP, hypoalbuminemia or increased white cell, neutrophil, and platelet counts predicted cancer OS regardless of the tumor stage." (PMID 26339617, 2015). "In the present study, we examined whether antecedent CRP could be used to predict future hypoalbuminemia in the perioperative period of colorectal surgery." (PMID 26530188, 2015). "However, 40% of the study population showed hypoalbuminemia and 55% had elevated levels of CRP, showing an inverse relation between them (r = −0.28), which has been strongly associated with inflammation, cardiac disease, and poor outcomes in several studies." (PMID 27347538, 2015). "Firstly, the GPS incorporates CRP and hypoalbuminemia and may be more suitable to reflect systemic inflammatory response than CRP alone." (PMID 25393117, 2014).
Hypoalbuminemia (continued). "The GPS, which is based on both serum elevation of CRP and hypoalbuminemia, may enable a better appreciation of effects of the tumor on both ongoing systemic inflammation and malnutrition." (PMID 24452408, 2014). "Fifteen (4.4 %) patients had both elevated CRP and hypoalbuminemia." (PMID 24452408, 2014). "Moreover, COP-NLR resulted associated with tumour-related characteristics (type and dimension, invasivity and metastasis, operative curability, CEA) and SIR-related characteristics (high CRP, hypoalbuminemia, low BMI, and high NLR)." (PMID 24877056, 2014). "Therefore, the results of the present study are important, indicating significant association not only between RDW and CRP but also between RDW and hypoalbuminemia, which is a predictor of malnutrition and mortality." (PMID 24800077, 2014). "A study was done to assess the value of combination of hypoalbuminemia and an elevated circulating concentration of CRP as a prognostic score in patients with advanced gastrointestinal cancer and found that a cumulative score based on these two parameters was a useful prognostic indicator." (PMID 21176210, 2010). "Of the six patients with hypoalbuminaemia, all had an elevated C-reactive protein concentration." (PMID 16404432, 2006). "Indeed, this concept is consistent with the observation in the present study that all patients with hypoalbuminemia had an elevated C-reactive protein concentration." (PMID 16404432, 2006). "Recently, we have shown that, using established cutoffs, a combination of an elevated C-reactive protein and hypoalbuminaemia, the Glasgow Prognostic score (GPS) has prognostic value, independent of stage and performance status, in patients with inoperable non-small-cell lung cancer." (PMID 16404432, 2006). "Approximately, 20% had hypoalbuminaemia and 80% had an elevated C-reactive protein concentration." (PMID 12966420, 2003). "Additionally, analyzing by chi-square test and Fisher’s exact test showed that age, B-symptoms, hypoalbuminemia, ECOG and plasma cell type were significantly associated with high serum CRP level in patients with iMCD, and that fibrinogen levels was positively correlated with CRP level." (PMID 40309739, 2025). "Third, factors causing hypoalbuminemia other than liver disease, such as malnutrition or inflammatory state, may not have been fully excluded because inflammation markers (C-reactive protein) or Controlling Nutrition Status scores were not compared." (PMID 41008815, 2025). "Thus, hypoalbuminemia or elevated CRP has been found to be related to cancer cachexia." (PMID 39098146, 2024). "Thus, a high HS-mGPS combined with a high CRP and hypoalbuminemia may indicate strong systemic inflammation and poor nutritional status and be associated with poor survival outcomes in cancer patients." (PMID 36674837, 2023). "In addition to the typical manifestations of NS, such as massive proteinuria, hypoalbuminemia, and hyperlipidemia, IgAN-NS patients exhibited higher levels of inflammatory indicators such as CRP and fibrinogen, as well as more pronounced glomerular mesangial proliferation." (PMID 37850851, 2023). "Thus, we hypothesized HD patients with lower Mg × K is equivalent to hypoalbuminemia and high CRP level, i.e., MIA syndrome, which make “Mg × K” lost of significance in predicting power in the analysis of Cox proportional method." (PMID 38092856, 2023). "Therefore, most PIMS patients have elevated levels of ESR and CRP, ferritin, D-dimers, LDH, and procalcitonin, but they may also have associated neutrophilia, thrombocytopenia and hypoalbuminemia." (PMID 36138657, 2022). "Hence, the effect of hypoalbuminemia without elevated CRP levels on the risk and prognosis of patients with HNC should be addressed in the analysis." (PMID 36079741, 2022).
Hypoalbuminemia (continued). "There was increase in value of inflammatory markers and enzymes, such as C-reactive protein (CRP) (117 mg/L) and D-dimer (9.62 mcg/ml), ferritin (1650 ng/mL), fibrinogen (650 mg/dL), aspartate aminotransferase (55 U/L), lactate dehydrogenase (467 U/L) with hypoalbuminemia (2.7 g/dL)." (PMID 36705185, 2022). "Thus, most of the PIMS patients have elevated levels of ESR and CRP, ferritin, D-dimers, LDH, and procalcitonin, but there may also be associated neutrophilia, thrombocytopenia and hypoalbuminemia." (PMID 36138657, 2022). "In addition, we found that the subjects in the group of “normal TSAT low iron” had highest percentage of low TIBC (39.4% with TIBC < 200 μg/dL), as well as the highest percentage of hypoalbuminemia (32.7% with Albumin < 3.5 g/dL) and elevated CRP levels (40.6% with CRP > 3 mg/L)." (PMID 33863963, 2021). "However, hypoalbuminemia combined with CRP is part of the modified Glasgow Prognostic Scale (mGPS)." (PMID 33446148, 2021). "This confirmed elevated CRP (201 mg/L; (<10 mg/L)), ferritin (362 μg/L; (14–124 μg/L)), D-dimers (5.92 μg/mL; (0.19–0.5 μg/mL)), NT-proBNP (7279 ng/L; (<125 ng/L)), initially normal troponin levels, hypoalbuminemia (18 g/L; (35–50 g/L)) and positive IgG-antibodies for SARS-CoV-2." (PMID 34438603, 2021). "Also, elevated CRP and hypoalbuminemia were identified in 87.5% and 50% of patients." (PMID 34776007, 2021). "Patients with hypoalbuminaemia had significantly lower serum haemoglobin (9.3 ± 1.7 versus 10.1 ± 1.5; p = 0.001) and eGFR (8.7 ± 3.4 versus 10.4 ± 4.6; p = 0.003), and higher serum ferritin (603.0 ± 221.0 versus 333.7 ± 185.7; p = 0.009) and CRP (7.3 ± 2.4 versus 2.5 ± 1.7; p < 0.001)." (PMID 34640538, 2021). "Also, infection or higher levels of inflammation reflected by the higher CRP-levels in hypoalbuminemic patients could lead to capillary leakage of albumin resulting in hypoalbuminemia." (PMID 31095609, 2019). "Besides, weight loss, hypoalbuminemia, elevated ESR or increased CRP may be regarded as the indications of CE for CAP patients." (PMID 29465542, 2018). "However, adding GI symptom score or CRP into the multivariable regression analysis, did not attenuate the association between lower eGFR and lower albumin or hypoalbuminemia." (PMID 26651991, 2015). "However, it is unclear whether antecedent CRP could be used to predict future hypoalbuminemia in the perioperative period of colorectal surgery." (PMID 26530188, 2015). "The combination of the increased CRP values and hypoalbuminemia may be due to one of the following: (a) patients' malnutrition (hypothrepsia) or (b) reactive response (tissue stress) due to the existence of cancer cells that activate the production of acute phase proteins." (PMID 26339617, 2015). "However, it is unclear whether antecedent CRP could be utilized to predict future hypoalbuminemia in the perioperative period in colorectal surgery." (PMID 26530188, 2015). "Laboratory testing demonstrated marked leucocytosis, eosinophilia, elevated erythrocyte sedimentation rate (ESR) and C-reactive protein (CRP), sterile pyuria, hypoalbuminemia and elevated alpha- and beta-globulins." (PMID 42100062, 2026). "Laboratory testing showed elevated C-reactive protein (CRP) and lactate dehydrogenase (LDH) levels, along with mild hypoalbuminemia." (PMID 40755567, 2025). "Serial labs demonstrated persistent inflammation (C-reactive protein (CRP) 321 → 171 → 121 mg/L) with stable renal function and mild hypoalbuminemia." (PMID 41393051, 2025). "Preliminary investigations included blood tests with full blood count, renal profile, bone profile, liver function test and C-reactive protein (CRP), which showed severe hypoalbuminemia, microcytic anaemia and hyperlipidaemia." (PMID 40698215, 2025). "Laboratory parameters indicated leucocytosis with neutrophilic predominance, elevated CRP, acute kidney injury (AKI) stage 2, and hypoalbuminemia." (PMID 41246573, 2025).
Hypoalbuminemia (continued). "Hypoalbuminemia was also more prevalent among IMV-supported patients (81.3% vs. 50.5%, p < 0.001), as were elevated CRP, procalcitonin, and lactate levels." (PMID 40869586, 2025). "Biological tests revealed an inflammatory syndrome with a C-reactive protein (CRP) of 132 mg/l, and serum protein electrophoresis showed hypoalbuminemia (31 g/l), hyper-α1 (4.1 g/l), and polyclonal hypergammaglobulinemia (36.5 g/l)." (PMID 40852710, 2025). "Of note, she had mild leukopenia (3.72 × 10^9/L), significant anemia (hemoglobin 74 g/L), hypoalbuminemia (24.8 g/L), hyperuricemia (611 μmol/L), and elevated inflammatory markers (ESR 37 mm/h, CRP 71.3 mg/L, IL-6 54.37 pg/mL)." (PMID 40726983, 2025). "A laboratory examination revealed elevated inflammatory markers, including a C-reactive protein (CRP) level of 0.47 mg/dL, and hypoalbuminemia with an albumin level of 3.2 g/dL." (PMID 40178693, 2025). "Clinically, low glutamine levels correlate with poor prognostic indicators—such as advanced age, tumor progression, hypoalbuminemia, elevated Carcinoembryonic Antigen (CEA), and C-reactive protein (CRP)—and predict shorter survival outcomes." (PMID 40951358, 2025). "Initial blood workup showed a platelet count of 27,000/μL and hemoglobin level of 6.2 g/dl, hypoalbuminemia, acute kidney injury, in addition to elevated lactate dehydrogenase (LDH), C-reactive protein (CRP), and sedimentation rate (ESR), and low fibrinogen." (PMID 39184660, 2024). "Laboratory findings indicated elevated levels of alkaline phosphatase (ALP) and C-reactive protein (CRP), along with severe hypoalbuminemia." (PMID 38540266, 2024). "Inflammatory cytokine, interleukin-6, contributes to the production of C-reactive protein (CRP) and the development of hypoalbuminemia." (PMID 38473433, 2024). "For instance, in patients with infections, the most common blood test abnormalities include elevated inflammatory markers such as C-reactive protein (CRP) or erythrocyte sedimentation rate (ESR), high neutrophil counts, and hypoalbuminemia." (PMID 39544385, 2024). "Nevertheless, patients with a GPS of 1 due to hypoalbuminemia, had a higher 3-year overall survival rate compared to patients with a GPS of one due to an elevated CRP level (p = 0.0094)." (PMID 39061188, 2024). "In clinical practice, it is common to observe elevated C-reactive protein (CRP) levels in critically ill patients, accompanied by hypoalbuminemia, indicating acute inflammatory responses and nutritional compromise, respectively." (PMID 39035503, 2024). "Significant predictors of mortality were elevated creatinine kinase, AST, BUN, ALT, and potassium; hypoalbuminemia during D1,2; elevated CRP, BUN, and potassium during D3,4; and elevated CRP and BUN during D5,6." (PMID 38379568, 2024). "This study illustrates variability in MIS-C symptoms and laboratory markers across different age groups and identifies severity predictors—higher CRP, PCT, BNP and hypoalbuminemia." (PMID 39596959, 2024). "Common laboratory findings in the three cases included elevated levels of CRP and ALP and severe hypoalbuminemia with normal immunoglobulin level." (PMID 38540266, 2024). "All had elevated CRP levels, median 226 mg/L (IQR 122.5–361), and hypoalbuminemia, with a median albumin value of 2.2 g/L (IQR 1.84–2.46)." (PMID 35967584, 2022). "Factors significantly correlated with subsequent biologic therapy were perianal disease, complicated disease behavior, high PCDAI (CD), fatigue, hypoalbuminemia, high PUCAI (UC) and fever, fatigue, hypoalbuminemia, hypoproteinemia, and elevated CRP (IBD)." (PMID 36291494, 2022). "Leukopenia, thrombocytopenia, high C-reactive protein (CRP) levels, coagulopathy and hypoalbuminemia were the characteristic laboratory findings." (PMID 36365057, 2022). "The common investigation findings include elevated inflammatory markers like C-reactive protein (CRP), D-dimer, erythrocyte sedimentation rate (ESR), and procalcitonin with hypoalbuminemia." (PMID 35340456, 2022).